LINC00582 (long independently transcribed non-coding RNA 582)
Synonyms: SMILO
Gene: Long non-coding RNA gene on chromosome 1 (231,591,292 to 231,612,242, reverse strand). Ensembl gene ENSG00000229228.
Diseases named in the same sentence as LINC00582 in open-access papers:
LINC00582 is named in the same sentence as 2 diseases in open-access papers, as found by Europe PMC text mining. Sharing a sentence is not in itself a finding about the gene and the disease. The quoted sentences say what the papers report.
melanoma (1 paper, 2024). A malignant, usually aggressive tumor composed of atypical, neoplastic melanocytes. "Previous studies have employed genes such as IGKV1D-42, IGLV5-37, IGKV2D-29, IGHV3-7, IGKV3D-11, and LINC00582 to construct prognostic models for tumors such as melanoma." (PMID 38502270, 2024).
LINC00582 also shares sentences with these, for which no sentence is quoted: myeloma (1 paper).